USP14 (ubiquitin specific peptidase 14)
Diseases named in the same sentence as USP14 in open-access papers (continued):
Sharing a sentence is not in itself a finding about the gene and the disease.
cancer (continued). "Indeed, treatment of an USP14 inhibitor IU1 did not significantly affect FASN levels in cancer cells." (PMID 34948233, 2021). "However, when FASN and USP14 were inhibited together, there were no synergistic effects on cancer cell death compared to inhibition of FASN alone." (PMID 34948233, 2021). "Consequently, we demonstrate that USP14 regulates proliferation of the cancer cells in a fatty acid synthase-independent manner, and targeting USP14 in combination with FASN may not be a viable method for effective cancer treatment." (PMID 34948233, 2021). "However, the role of USP14 in cancer cell death has not yet been clarified." (PMID 31653087, 2019). "Moreover, previous reports have indicated that FASN serves as a substrate for USP14 in hepatocytes, but other reports suggest that FASN levels in cancer cells are not considerably impacted by the USP14 inhibitor IU1, suggesting that FASN may not be a direct substrate of USP14 in cancer cells." (PMID 39048965, 2024). "Inhibition of USP14 by IU1 or siRNAs targeting USP14 did not reduce FASN levels but rather increased FASN levels and activity in cancer cells." (PMID 34948233, 2021). "Therefore, we conclude that USP14 inhibition does not compensate for the weakness of the FASN inhibitor and suggest that the use of both inhibitors together as cancer therapeutics is undesirable." (PMID 34948233, 2021). "However, in HepG2 cancer cells, either UCHL5 or USP14 knockdown did not abrogate CuPT-mediated ubiquitinated protein accumulation." (PMID 24912524, 2014). "Taken together, these results indicated that FASN binds to USP14 but may not be a direct substrate of USP14, and the expression level of USP14 is more important in modulating FASN levels than the activity of USP14 in cancer cells." (PMID 34948233, 2021).
tumor (99 papers, 2013 to 2026). "USP14 has been implicated in promoting tumour growth and survival by stabilising oncogenic proteins and modulating signalling pathways." (PMID 40374593, 2025). "Mice bearing USP14-deficient tumors responded more robustly to oxaliplatin, with a substantial reduction in both tumor size and weight by approximately 32% and 67% (oxaliplatin treatment), as compared to control tumors." (PMID 40316942, 2025). "Overexpression of USP14 promotes tumour cell proliferation and is associated with the poor prognosis of NSCLC." (PMID 36969062, 2023). "Next, subcutaneous xenograft models showed that USP14 deficiency significantly inhibited the growth of tumours, and decreased the expression of TAZ and Ki-67." (PMID 35906484, 2023). "Upregulation of USP14 in NSCLC cells has been closely associated with increased tumor cell proliferation and the shorter overall survival of patients." (PMID 35069211, 2021). "Additionally, USP14 is implicated in inhibiting tumor-specific apoptosis in ibrutinib-resistant Waldenström macroglobulinemia (WM) cells." (PMID 38702734, 2024). "IHC results implied that deficiency of USP14 declined Ki-67 expression in tumor tissues." (PMID 37082728, 2023). "We then investigated whether overexpression of USP14 could restore the delayed tumor progression phenotype in YTHDF1-deficient AGS and BGC-823 cells." (PMID 33791305, 2021). "We herein found that YTHDF1 could promote USP14 protein translation in a m6A-dependent manner and USP14 overexpression reversed the tumor suppressive effects caused by YTHDF1 knockdown in GC cells." (PMID 33791305, 2021). "Inhibiting USP14 reversed their pro-tumor functions, promoted M1 polarization, enhanced tumor cell killing, and activated effector T cells." (PMID 42058892, 2026). "RT treatment significantly augmented tumor regression, as evidenced by reduced tumor volume in the USP14-KO group compared to control cells." (PMID 40595451, 2025). "In summary, our study highlights the role of USP14 in promoting tumor progression by regulating the BAG4/PRKN-mediated mitophagy pathway." (PMID 40316942, 2025). "Histopathological analysis revealed that after RT treatment, the reduction in tumor cells was substantially greater in USP14-KO xenografts than in USP14-WT xenografts." (PMID 40595451, 2025). "USP14-mediated SIRT1 stabilization promotes M2 macrophage polarization via SIRT1/PGC1-α-mediated lipid oxidation in mouse tumor models." (PMID 40567502, 2025). "USP14 exhibits significantly higher expression in tumor tissues of HCC patients compared to para-cancerous and normal liver tissues." (PMID 40607251, 2025). "In HNC, overexpression of RELA has been associated with tumor progression, resistance to chemotherapy, and increased invasiveness through pathways such as IKK-NFκB/RELA and USP14-mediated signaling." (PMID 40606440, 2025). "This study further revealed that YTHDF1 promotes USP14 protein translation in an M6A-dependent manner and that overexpression of USP14 can counteract the tumor-suppressive effects of YTHDF1 knockdown in GC cells." (PMID 41312360, 2025). "Herein, FABP5 was identified as a novel substrate of USP14, which contributes to tumor formation by maintaining the stability of oncoproteins." (PMID 39928282, 2025). "The analysis demonstrated a significant disparity in USP14 expression between tumor and adjacent non-tumor tissues, underscoring USP14’s differential expression and warranting its selection for further investigation." (PMID 40316942, 2025). "To investigate the effect of USP14 on LV’s regulation of Survivin protein stability in vivo, we used a mouse xenograft tumor model established with MDA-MB-231 cells." (PMID 40497992, 2025).
tumor (continued). "High expression of USP14 and BAG4 was associated with poor overall survival, highlighting their potential as markers for aggressive tumor behavior." (PMID 40316942, 2025). "Transient S100A11 overexpression partially but significantly rescued the USP14 knockdown-induced tumour growth suppression." (PMID 40374593, 2025). "Consistent with our in vitro data, knockdown of USP14 significantly suppressed tumor growth, while BAG4 overexpression abrogated this inhibitory effect." (PMID 40316942, 2025). "Another inhibitor, VXL1570, also inhibits the functions of USP14 and UCHL5, which when used alone caused tumor reduction in Waldenstrom's macroglobulinemia tumor-bearing mice." (PMID 39759114, 2025). "Studies have shown that USP14 regulates tumour growth and progression by inhibiting deubiquitination activity in the 19S proteasome." (PMID 40988122, 2025). "Functional analyses reveal that knocking down USP14 reduces tumor growth, and increases sensitivity to oxaliplatin." (PMID 40316942, 2025). "Overexpression of USP14 promoted cell proliferation and migration, while downregulation of USP14 inhibited tumor cell proliferation, migration and invasion, with declined cell apoptosis." (PMID 38819674, 2024). "We also verified a novel mechanism for USP14’s involvement in tumor growth and metastasis via its regulation of PFKL." (PMID 38388430, 2024). "The results of this analysis showed that USP14 expression in OSCC tumor tissues was significantly higher than that in adjacent normal tissue samples, which is consistent with what we found in a previous study." (PMID 38388430, 2024). "Our results indicated that USP14 was aberrantly overexpressed in OSCC tumor tissues compared to normal ones." (PMID 38388430, 2024). "Our findings provide novel insights into the tumor-promoting role of USP14 and establish mechanistic foundations for USP14-targeted therapies." (PMID 38388430, 2024). "Our results showed that, compared to the control group, the stable knockdown of USP14 significantly decreased the tumor volumes and weights." (PMID 38388430, 2024). "Overexpression of CIB1 significantly alleviated the USP14 knockdown-induced inhibition of tumor growth and tumor weight." (PMID 38993552, 2024). "Prognostic analysis indicated that elevated USP14 expression was correlated with advanced tumor stage, multiple tumor numbers, and poor prognosis in patients with HCC (cohort 1, n=170)." (PMID 38993552, 2024). "Collectively, our findings provide novel insights into the tumor-promoting role of USP14 and establish mechanistic foundations for USP14-targeting therapies." (PMID 38388430, 2024). "We then assessed the expression of the proliferation marker Ki-67 in the tumor tissues via immunohistochemical staining and found that it was significantly reduced in USP14-depleted tumors." (PMID 38388430, 2024). "Subcutaneous xenograft and liver metastasis models were established to further confirm the roles of TAZ in USP14-mediated tumour progression in vivo." (PMID 35906484, 2023). "Through colony formation assay and cell growth curve generation, we assessed the influence of USP14 on tumor phenotype in SW48 cells in vitro." (PMID 36693850, 2023). "USP14 inhibition in tumor mice breaks the immune-suppressive action exhibited by tumor-promoting macrophages, meanwhile greatly reshaping the immune TME in GC." (PMID 37658402, 2023). "In this study, therefore, we identified USP14 as a tumor proliferation enhancer and a substantially hyperactive deubiquitinase in HNSCC samples, implying a poor prognosis prediction." (PMID 37686660, 2023). "Downregulating USP14 increases dendritic cells (DCs) sensing of irradiated-tumor cells in vitro, suggesting that repressing USP14 promotes systemic antitumor immunity." (PMID 37917013, 2023). "When tumor cells endocytose the nano‐zinc carriers, high concentrations of USP14 siRNA are released in cells to effectively treat NSCLC." (PMID 37035133, 2023).
tumor (continued). "Consistently, defective USP14 in vivo significantly diminished HNSCC tumor growth and lung metastasis compared to the control group." (PMID 37686660, 2023). "USP14 inhibition led to a marked reduction in the tumor growth, augmented the infiltration of cytotoxic T cells, reduced the infiltration rate of Regulatory T cells (Tregs) and promoted the response to anti-PD-1 therapy." (PMID 37830596, 2023). "USP13 (F = 24.25, p = 1.00 × 10−05) and USP14 (F = 11.88, p = 1.17 × 10−03) expression were both decreased in CPh compared to non-tumor tissue." (PMID 37892185, 2023). "IHC and WB results revealed an upregulation of the USP14 protein level in the tumor tissues of the USP14 group compared to the vector group." (PMID 37917013, 2023). "It observed that knockdown of TAZ decreased the growth of the USP14-overexpressing tumours, and inhibited the expression of Ki67 and TAZ." (PMID 35906484, 2023). "These tumor phenotype experiments indicated that USP14 overexpression led to considerably increased SW48 number of viable cells (fold increase)." (PMID 36693850, 2023). "A dysregulation of USP14 can alter key cellular processes that in turn can contribute to tumor progression, neurodegenerative pathologies, and inflammation." (PMID 37711852, 2023). "USP14 is also a well-known tumor promoter similar to USP10 which contains USP domain in C-terminal and ubiquitin-like (UBL) domain in N-terminal to regulate proteasomal activity, and BL1 and BL2 domains are also key factors for USP14 activity." (PMID 36582601, 2022). "YTHDF1 also increased USP14 levels in an m6A-dependent manner, and USP14 overexpression reversed the tumor-suppressive effects elicited by YTHDF1 silencing." (PMID 36497313, 2022). "Previous studies have shown that USP14 is highly expressed in a variety of malignancies and plays a critical role in tumor progression." (PMID 36423684, 2022). "Immunohistochemical (IHC) experiments were then performed to detect the expression level of USP14 in xenograft tumor derived from Ishikawa cells." (PMID 36423684, 2022). "USP14 interacts with murine double minute 2 and stabilizes murine double minute 2, leading to tumor progression in cervical cancer." (PMID 36423684, 2022). "More importantly, intraperitoneal administration of anti-PD-1 exerted more effective tumor suppression and survival improvement in the usp14 shRNA group than in the control group." (PMID 36163134, 2022). "USP14 has also been revealed its unique role in tumor progression, and several selective USP14 inhibitors have been developed for targeted therapy, such as IU1 and IU1-47." (PMID 36582601, 2022). "Collectively, these data demonstrated that USP14 functioned as a key regulator of immune suppression by modulating IDO1 levels in tumor cells." (PMID 36163134, 2022). "The mice bearing usp14 shRNA-expressing MC38 cells showed moderately decreased tumor weights and increased survival compared with the mice implanted with control MC38 cells." (PMID 36163134, 2022). "USP14 activation promotes tumor progression by increasing cell proliferation and inhibiting apoptosis." (PMID 36163134, 2022). "Tumor volumes and tumor weight exerted remarkably declined in the combination therapy as compared with the lentivirus-mediated USP14 knockdown or IU1 alone treatment." (PMID 34420039, 2021). "In normal liver tissues (normoxia dominated), the USP14 protein level is lower than that of tumor tissues, and HIF1-α is lower expressed." (PMID 34420039, 2021). "USP14 promotes tumor growth by regulating DNA damage response or ER stress-mediated autophagy in non-small cell lung cancer cells." (PMID 33928122, 2021).
tumor (continued). "In vitro and in vivo studies have shown that genetic and pharmacological inhibition of USP14 induces degradation of an androgen receptor (AR), favoring tumor suppression in AR-positive breast cancer cells or prostate cancer cells." (PMID 33928122, 2021). "VLX1570, a b-AP15 analogue with higher potency and higher selectivity for USP14, demonstrated anti-tumor activity, and enhanced survival in MM xenografts." (PMID 33036368, 2020). "A proteasome inhibitor, b-AP15, that targets 19S regulatory particle associated DUBs, including USP14 and UCHL5, showed anti-tumor activity." (PMID 33158118, 2020). "We identify two important tumor-associated pathways, i.e. autophagy and PTEN/AKT to directly regulate the function of USP14 in DSB repair." (PMID 31740976, 2020). "b-AP15 (also known as VLX1500) inhibited the activity of the deubiquitinases, ubiquitin C-terminal hydrolase 5 (UCHL5) and USP14, inducing tumor cells apoptosis and inhibiting tumor progression." (PMID 31988639, 2020). "USP14 is known to promote oncogenesis in several tumor types, and pharmacological inhibition of USP14 has been shown to effectively control tumor growth." (PMID 31740976, 2020). "A previous study has reported that USP14 inhibition using shRNA downregulates tumor cell proliferation." (PMID 31653087, 2019). "Our results corroborate those of a previous study wherein USP14 downregulation decreased tumor growth." (PMID 31653087, 2019). "In separate cohort of mice, we implanted subcutaneously USP14-depleted MCF-7 cells stably expressing USP14-specific shRNA or control shRNA and monitored tumor growth as they were treated with enzalutamide or vehicle." (PMID 31126320, 2019). "Mice bearing USP14 shRNA-expressing MCF-7 cells showed decreased tumor growth compared with mice implanted with MCF-7 cells expressing control shRNA." (PMID 31126320, 2019). "The inhibition of UCHL5 and USP14 deubiquitinase activity by WP1130 is expected to block the function of the proteasome in tumor tissue cells, but this still needs to be tested." (PMID 30319415, 2018). "The restoration of miR-320a expression can suppress GC cell proliferation, migration and invasion by targeting both USP14 and vimentin, which shows that miR-320a acts as a tumor suppressor in GC." (PMID 27448976, 2017). "In short, these results suggest that the tumor suppressor role of miR-320a in GC cells is mediated or at least partially mediated by the downregulation of USP14 and vimentin expression." (PMID 27448976, 2017). "Together, these results indicate that miR-320a downregulates USP14 and vimentin and functions as a tumor suppressor in GC cells." (PMID 27448976, 2017). "Several studies suggest that USP14 is a tumor-promoting factor via enhancement of the Wnt/β-catenin signaling pathway." (PMID 29039082, 2017). "Compared with PBMCs from healthy donors, USP14 mRNA expression was significantly elevated in WM tumor cell lines and primary WM cells (5.4-fold median increase; range, 2.8–19-fold)." (PMID 27813535, 2016). "In summary, we present compelling data on the targetability of the 19 S proteasome-associated DUBs, USP14 and UCHL5 with the use of VLX1570, which induces tumor-specific cell death, particularly in WM cells resistant to bortezomib or ibrutinib." (PMID 27813535, 2016). "Over-expression of USP14 was associated with poor prognosis in NSCLC patients and promoted tumor cell proliferation, which suggests that USP14 is a tumor-promoting factor and a promising therapeutic target for NSCLC." (PMID 23702845, 2013). "USP14 inhibition also increased PD-L1 expression on tumor cells, alleviating T cell suppression." (PMID 42058892, 2026). "Consequently, it is imperative to evaluate the influence of targeting USP14 on type I interferon (IFN) -mediated anti-tumor immune responses." (PMID 40595451, 2025). "Finally, a mouse xenograft model was employed to study USP14’s role in tumor growth and oxaliplatin sensitivity." (PMID 40316942, 2025).